THNSL2 (threonine synthase like 2)
Description:
[Isoform 1]: Acts as a catabolic phospho-lyase on both gamma- and beta-phosphorylated substrates. Degrades O-phospho-threonine (PThr) to alpha-ketobutyrate, ammonia and phosphate (By similarity). [Isoform SOFAT]: Potent inducer of osteoblastic production of IL6. May act to exacerbate inflammation and/or bone turnover under inflammatory conditions.
Synonyms: TSH2; SOFAT; FLJ10916; THS2
Tractability: Antibody: UniProt places it where antibodies can reach, with medium confidence; its Gene Ontology location is reachable by antibodies, with medium confidence. PROTAC: its protein half-life has been measured.
Gene: Protein-coding gene on chromosome 2 (88,170,295 to 88,186,636, forward strand). Ensembl gene ENSG00000144115.
Subcellular location: Secreted (Isoform SOFAT)
Gene Ontology:
Molecular function: phosphatase activity; pyridoxal phosphate binding; serine binding; threonine synthase activity
Cellular component: extracellular region
Genetic constraint (gnomAD): Loss-of-function variants: 33 observed, 39.34 expected, observed/expected ratio (o/e) 0.84, 90% interval 0.63 to 1.12. The upper end of that interval is the gene's LOEUF score, 1.12, which puts it in group 4 of 6, group 1 being the genes least tolerant of losing a copy. Missense variants: 485 observed, 577.49 expected, observed/expected ratio (o/e) 0.84, 90% interval 0.78 to 0.9. Synonymous variants: 225 observed, 234.12 expected, observed/expected ratio (o/e) 0.96, 90% interval 0.86 to 1.07.
Homologues: Orthologues: chimpanzee THNSL2 (99% identical), macaque THNSL2 (96% identical), rabbit THNSL2 (85% identical), pig THNSL2 (84% identical), rat Thnsl2 (84% identical), mouse Thnsl2 (83% identical), guinea pig THNSL2 (83% identical), dog THNSL2 (76% identical), tropical clawed frog thnsl2 (59% identical), zebrafish thnsl2 (51% identical), Caenorhabditis elegans F13B12.4 (12% identical), Caenorhabditis elegans F01D4.8 (11% identical), and 5 more. Paralogues in human: CBS (15% identical), THNSL1 (15% identical), SDS (12% identical), SDSL (11% identical), SRR (11% identical).
Diseases named in the same sentence as THNSL2 in open-access papers:
THNSL2 is named in the same sentence as 10 diseases in open-access papers, as found by Europe PMC text mining. Sharing a sentence is not in itself a finding about the gene and the disease. The quoted sentences say what the papers report.
chordoma (2 papers, 2022 to 2023). Chordomas are rare malignant tumors arising from embryonic remnants of the notochord in axial skeleton. "A recent multi-omic study of chordoma cell lines identified CA-2 and THNSL2 as potentially druggable genes in chordoma." (PMID 37434245, 2023). "In an integrated multi-omics analysis, CA2 and THNSL2 were identified in the switched compartments, cell-specific boundaries, and loops, indicating their tumorigenic roles in chordoma." (PMID 36185236, 2022).
breast carcinoma (1 paper, 2014). "The cis-eQTL associations of H1F0, HMBOX1, and THNSL2 genes are also represented in Breast Cancer." (PMID 25133526, 2014). "The cis-eQTL associations of 7 genes (TAPBPL, H1F0, SERPINB9, HMBOX1, MGST3, TMBIM4, THNSL2) are shared between GBM and cell lines/normal tissues; the association of 4 genes (TAPBPL, H1F0, HMBOX1, THNSL2) are common between GBM and Breast Cancer." (PMID 25133526, 2014).
cholangiocarcinoma (1 paper, 2021). A carcinoma that arises from the intrahepatic biliary tree (intrahepatic cholangiocarcinoma) or from the junction, or adjacent to the junction, of the right and left hepatic ducts (hilar cholangiocarcinoma). "Finally, six AS events, SLC38A10-44114-AT, IL18BP-17488-RI, NBPF10-5531-ES, THNSL2-54469-ME, FAM3A-90629-ES, and KIAA1432-85794-AT, were identified as independent risk factors for OS in cholangiocarcinoma." (PMID 34055632, 2021).
Obesity (1 paper, 2016). Accumulation of substantial excess body fat. "THNSL2 encodes threonine synthase like 2 and SNPs in this locus have been associated with obesity." (PMID 27322064, 2016).
THNSL2 also shares sentences with these, for which no sentence is quoted: periodontitis (2 papers); rheumatoid arthritis (2); infection (1); nephronophthisis (1); tumor (1); viral infection (1).